SIRPA (signal regulatory protein alpha)
Diseases named in the same sentence as SIRPA in open-access papers (continued):
Sharing a sentence is not in itself a finding about the gene and the disease.
tumor (continued). "However, suppression was not fully reversed by α-SIRPα blockade implying that SIRPα sites were not fully occupied, or that other factors also contribute to the suppressive potential of tumor-conditioned myeloid cells." (PMID 38577107, 2024). "Besides enhancing phagocytosis via inhibiting the interaction between CD47 and SIRPa, anti-CD47 nanobodies might offer a targeted approach to deliver transgenes to tumor cells expressing CD47." (PMID 38247566, 2024). "This strategic combination of the “eat me” signal from FcγRIIa and the suppression of the “don’t eat me” signal via SIRPα inhibition endowed CAR-shSIRPα-M with increased phagocytic activity and induced an M1-like phenotype, resulting in significant cytotoxic effects on HER2-positive tumor cells." (PMID 39379603, 2024). "Moreover, within SPP1 + macrophage population, SIRPα positive cells were found to be closer to tumor cells than SIRPα negative cells." (PMID 39696410, 2024). "We observed that the combination of NextA and anti-SIRPα did not decrease the tumor growth." (PMID 38414061, 2024). "Importantly, CD47 expression was extremely high in SKOV3, SKBR3, DLD-1, and ASPC1 tumor cells, and coculture with these tumor cells significantly increased SIRPα expression in UTD and CAR macrophages, whereas CAR-shSIRPα macrophages maintained low SIRPα levels." (PMID 39379603, 2024). "Furthermore, we found that SIRPA (the “don't eat me” molecular CD47 ligand) was overactivated in MRC1+TAMs and expressed on most of the tumor‐infiltrating macrophages, indicating that macrophages are important mediators of tumor immunosurveillance in the PCa microenvironment." (PMID 38483933, 2024). "In light of these data, SIRPα-mediated negative control of tumor-infiltrating phagocytes may be a significant host-mediated mechanism of tumor-associated acquired radioresistance." (PMID 37291116, 2023). "Thus, we thought that lack of SIRPα exerted anti‐tumour effects possibly by increasing phagocytosis activity of MPs and NPs by suppressing STAT3 signalling." (PMID 36419386, 2023). "Binding to CD172a (the signal regulatory protein α, SIRPα) on macrophage, CD47 on tumor cells can send the inhibitory signal “do not eat me” to macrophages so as to maintain the immune tolerance of own cells, prevent tumor cells from being phagocytized, and inhibit tumor antigen presentation." (PMID 37241964, 2023). "In addition to the CD47/SIRPα cascade, CD40 agonists re-educate TAMs into M1 macrophages to restore cancer immune surveillance, and the combination therapy of anti-PD1/PD-L1 and anti-CD40 also enhances anti-tumor efficacy." (PMID 36845095, 2023). "Therefore, whether the NVs express fusion protein of PD‐1 and SIRPα high‐affinity consensus (HAC) can integrate all the advantages and have synergistic effects on tumour immunomodulation becomes attractive." (PMID 37974395, 2023). "Furthermore, these inhibitory mechanisms may impede phagocytosis in wild type phagocytes that express SIRPα and CD47 of any cellular target on which CD47 is expressed (e.g., red blood cells, platelets and tumor cells)." (PMID 37872624, 2023). "Lack of SIRPα inhibited LLC cells growth in KO mice, associated with reduced infiltrating PD‐1+CD8+ T cells and production of IL‐6 from infiltrating macrophages and neutrophils in tumour tissues." (PMID 36419386, 2023). "Previous studies have shown that targeting the CD47/SIRPα axis with anti-CD47 agents (including antibodies and SIRPα-Fc fusion proteins) promotes the phagocytosis of tumor cells by macrophages in vitro, and inhibits tumor growth in many human tumor xenograft models." (PMID 36650558, 2023). "Thus, in patients with normal or high MHCI expression in tumor cells, drugs targeting the MHCI/LILRB1 axis may facilitate antitumor immune responses and act synergistically with drugs targeting the CD47/SIRPα axis." (PMID 35892835, 2022).
tumor (continued). "However, the anti-SIRPα antibody alone neither inhibited tumour growth (P>0.05) nor prolonged the survival time of tumour-bearing mice (P>0.05)." (PMID 36310169, 2022). "Whether DC killing of tumor cells mediated by NI-1701 depends primarily on the blockade of the CD47/SIRPα axis or on Fc-dependent mechanisms has not been elucidated yet and remains to be clarified." (PMID 35538512, 2022). "Targeting CD47 with non-FcR activating agents or directly targeting SIRPα could avoid an important part of the killing of non-tumor cells bearing CD47 while preserving the tumor cytotoxic capacity of PMN." (PMID 35795660, 2022). "Tail-vein injections of these Antibody-primed Plus SIRPα-Blocked (A’PB) engineered macrophages previously proved to be safe and effective against subcutaneous human tumor lines in immunodeficient mice but had not been tested on metastases in syngeneic, immunocompetent models." (PMID 35454837, 2022). "CD47- SIRPα interaction leads to recruitment of downstream Src homology-2 domain-containing protein tyrosine phosphatases (SHP-1 and SHP-2), preventing the accumulation of myosin-IIA at the phagocytic synapse, thereby inhibiting macrophage-mediated tumor phagocytosis." (PMID 35883692, 2022). "Conversely, when EVs overexpress SIRPα, due to binding to CD47 on the surface of cancer cells, EVs disrupt the interaction of the cancer cell signaling CD47-SIRPα axis, resulting in increased phagocytosis of cancer cells by macrophages, thereby suppressing tumor growth." (PMID 36297672, 2022). "The researchers used transmembrane region structure of platelet-derived growth factor receptors and SIRPα avariant co-modified exosomes (SIRPα-exosomes), which can destroy the interaction of CD47-SIRPαleads to increase the number of cells phagocytized by macrophages, thereby inhibiting tumor growth." (PMID 34973131, 2022). "Moreover, the blocking interaction of CD47 and SIRPα was also demonstrated to reprogram MDSC and tumor-associated macrophages (TAMs) as non-suppressive." (PMID 35746616, 2022). "Interestingly, AO176 blocked the CD47/SIRPα interaction to stimulate phagocytosis of tumor cells, and also directly killed tumor cells (non-ADCC)." (PMID 35418166, 2022). "Some reports have shown that TAM infiltration is usually positively correlated with SIRPα expression, which might be explained by stimulation of SIRPα expression in macrophages by CD47 self-antigen expressed in tumors, although the extent of this stimulation varies depending on tumor type." (PMID 34573091, 2021). "Therefore, in patients with normal or high expression of MHCI on tumor cells, drugs targeting the MHCI/LILRB1 axis may promote anti-tumor immune responses and play a synergistic effect with drugs targeting CD47/ SIRPα axis." (PMID 34625124, 2021). "Furthermore, non-functional SIRPα variant soluble proteins in preclinical models and anti-CD47 mAb in non-Hodgkin’s lymphoma patients have been combined with rituximab, resulting in tumor regression." (PMID 34638388, 2021). "This compensatory pro-tumor mechanism post-RT, however, was explicitly absent in the Sirpα−/− TME." (PMID 34050181, 2021). "The rapid reduction of Sirpα−/− macrophages in the TME following IR argues that the RT-induced tumor elimination in Sirpα−/− mice maybe not due to direct phagocytosis or clearance of tumor cells by Sirpα−/− macrophages." (PMID 34050181, 2021). "EC tumor cells can also escape from immune surveillance by inducing DC-triggered TIL apoptosis under the influence of RCAS1, or by promoting the DC transformation into an immunosuppressive phenotype, with PD-L1 and SIRPα expression and IDO1 production, inhibiting CD8+ T cell activity." (PMID 33995371, 2021). "However, because ALX-148 is engineered based on the natural SIRPα allelic variant V1, it does not differentiate between CD47 expressed on tumor cells and RBCs, therefore anemia is still observed in clincial trials." (PMID 33790906, 2021).
tumor (continued). "Notably, CD47 sends “don’t eat me” signals by inhibiting phagocytosis of tumor cells and triggering an immune evasion and therefore serves as a myeloid-specific immune checkpoint when CD47 binds to signal regulatory protein α (SIRPα) that is an inhibitory receptor on macrophages and dendritic cells." (PMID 34305918, 2021). "Likewise, WT mice infused with Sirpα−/− macrophages in tumors did not curtail tumor progression in the absence of RT." (PMID 34050181, 2021). "CD47 transmembrane protein protects the nanovesicles from being phagocytized by binding to the signal regulatory protein alpha (SIRPα) and stimulating “do not eat me” signals, thus decreasing its systemic clearance in order to enhance the delivery to the tumor site." (PMID 34371702, 2021). "Interestingly, activated Sirpα−/− BMDMs did not phagocytose their engaged Tc to which they putatively presented tumor antigens." (PMID 34050181, 2021). "Because SIRPα from NOD/SCID mice bound human CD47 with an exceptionally higher affinity compared to that from other mouse strains, and even greater than hCD47, this strain is an ideal xenograft model for assessing the tumour inhibitory effect of our antibodies." (PMID 33449453, 2021). "Targeting TAM inhibitory (“do not eat”) signals-CD47/SIRPα axis by therapeutic SIRPα antibodies could inhibit tumor formation inAOM-DSS-induced CRC." (PMID 34667145, 2021). "Given that the binding of CD47 with SIRPα in tumor cells limits the anti-cancer immune response, it is possible that therapies that inhibit CD47 signaling in cancer cells would promote the phagocytosis of tumor cells by macrophages and thereby limit tumor growth." (PMID 32082311, 2020). "In addition to Sirpα in TAMs, CD47 in tumor cells can also be suppressed by other factors." (PMID 32296015, 2020). "In more aggressive and poorly immunogenic tumors, additional treatment modalities may be necessary to improve tumor control and eradication, such as triple combinations with tumor antigen specific antibodies, CD47/SIRPα antagonists, ICIs, vaccines, or chemotherapy." (PMID 33256806, 2020). "Studies showed that some CTCs can upregulate the expression of CD47 on their surface, which is identified by SIRPα (also known as macrophage fusion receptor) on the surface of macrophages and DCs, then transmitting the ‘do not eat me’ signal and inhibiting the clearance of tumor cells." (PMID 31980023, 2020). "The inhibitory receptor, signal regulatory protein-alpha (SIRPα), negatively regulates macrophage and DC phagocytic activity by interacting with its cognate ligand cluster of differentiation 47 (CD47) overexpressed on many types of cancer cells, increasing tumor invasion and metastasis." (PMID 32456204, 2020). "Moreover, anti-SIRPα treatment led to a marked increase in the number of tumor-infiltrating NK cells and CD8+ T-cells, and antibody-mediated depletion of these cells decreased the inhibitory effect of SIRPα blockade on tumor formation." (PMID 31801627, 2019). "Our research provided evidence that CD47 blockade could sensitize NSCLC to anti-angiogenic therapy and potentiate its anti-tumor effects by enhancing macrophage infiltration and tumor cell destruction, providing novel therapeutics for NSCLC by disrupting CD47/SIRPα interaction and angiogenetic axis." (PMID 31829270, 2019). "However, the studies that characterize SIRPα-expressing Mo/MΦs, especially in the tumor microenvironment, are lacking, possibly due to a low number of Mo/MΦs defined by well-known markers." (PMID 31611550, 2019). "In A549 xenograft model, tumor weight in VEGFR1-Fc group was 426.04 ± 64.26 mg versus 942.20 ± 130.27 mg of the isotype control (P < 0.0001), and the tumor weight in VEGFR1-Fc and SIRPα-Fc co-treatment group was 68.15 ± 35.64 mg (P < 0.0001 versus VEGFR1-Fc group)." (PMID 31829270, 2019).
tumor (continued). "The therapeutic success of anti-SIRPα blocking Abs in tumors SIRPα-positives, might be based on the activation of the ADCP mechanism against tumor cells by macrophages together with the elimination of the phagocytosis blockade exerted by the CD47-SIRPα interaction." (PMID 31921125, 2019). "On the other hand, high-affinity SIRPα monomers (~14 kDa) are not sufficient to induce macrophage phagocytosis, instead, act as an adjuvant to lower the threshold for phagocytosis in the presence of a separate, tumor-binding antibody." (PMID 30105024, 2018). "Although blocking the interaction between CD47 on tumor cells and SIRPα on the host macrophages and DCs induces antitumor immune responses, simultaneous interruption of the TSP1-CD47 signaling in tumor stromal cells, such as endothelial cells, may potentially facilitate tumor progression." (PMID 27283989, 2017). "Blocking CD47/SIRPα interaction could induce phagocytosis and enable DCs to cross-present tumor antigens through MHC class I molecules, which further activates CD8+ T cells that are specific for tumor antigens." (PMID 27863402, 2016). "In addition, activation of macrophage anti-tumor activity has been also an area of active investigation, in particular regarding the blockade of the binding between CD47 molecules and macrophage signal regulatory protein-alpha (SIRPα)." (PMID 26093091, 2015). "Furthermore, tumor-bearing mice exhibited enhanced intrathymic antigen uptake by Sirpα+ cDCs, but not by Sirpα− cDCs, when OVA protein was intravenously injected." (PMID 22815949, 2012). "However, blocking SIRPα did not result in tumor control in the single-arm group." (PMID 38414061, 2024). "Many studies have confirmed that blocking CD47 interaction with SIRPα can enhance cancer cell clearance via macrophage inhibition of CD47/SIRPα interaction, which may increase antigen cross-presentation, leading to an adaptive anti-tumor immune response with T-cell priming." (PMID 38136311, 2023). "Notably, a recent study demonstrated that the combination of CD47/SIRPα inhibition with activation of CD40 signaling using a SIRPα-Fc-CD40L fusion protein also enhances type I interferon responses in macrophages, increasing effector T cell activity, further blocking tumor growth." (PMID 33801234, 2021). "However, this anti-tumor effect lasted for 1-2 weeks, followed by differentiation of the donor macrophages toward non-phagocytic, high SIRPα TAMs, alluding to the high plasticity of macrophages in response to microenvironmental factors and the need for more permanent approaches." (PMID 33816242, 2021). "Notably, tumors infused with Sirpα−/− BMDMs in WT mice after IR also displayed similar robust expansion of GranzBhighp15E-reactive Tc, whereas those without infused Sirpα−/− BMDMs had poor induction of Tc (from 6 to 13%) that were mostly GranzBlow and lacked tumor-specificity (non-p15E reactive)." (PMID 34050181, 2021). "Indeed, all Sirpα−/− mice with small tumors, as well as most with medium tumors, that received local RT displayed completed responses, survived without apparent long-term adverse effects, and remained tumor-free for the rest of the study (>180 days)." (PMID 34050181, 2021). "Thus, innate checkpoint inhibition may enhance the anti-tumor effect of DNA damaging agents.CD47 is an immune checkpoint that binds signal regulatory protein alpha (SIRPα) and delivers a “do not eat” signal to suppress macrophage phagocytosis." (PMID 30400835, 2018). "Interestingly, even without cell-cell direct interaction, knockdown of SIRPα on macrophages could increase the migration of Cal-27 cells, suggesting that the substance released by macrophages may play a critical part in tumor migration." (PMID 27793032, 2016). "In addition, as tumor cells express SIRPα mRNA but no SIRPα protein, induction of SIRPα protein expression in these tumor cells by suppressing the expression of SIRPα-targeting miRNAs also provide a potential anti-tumor strategy." (PMID 27010069, 2016).
tumor (continued). "Tumor cells evade phagocytosis by overexpressing CD47, which engages SIRPα on macrophages to transmit a "do not eat me" signal." (PMID 41417432, 2025). "These in vitro findings demonstrate that SIRPα + CD209 + cells are radioresistant and exhibit significant upregulation of HLA-DR, independent of the presence of tumor cells, following radiation exposure." (PMID 40208335, 2025). "Tumor cells overexpress CD47, a transmembrane protein, to bind SIRPα and send a ‘do not eat me’ signal, preventing phagocytosis and allowing tumors to avoid immune destruction." (PMID 40070841, 2025). "Because F05 does not bind mouse-derived SIRPα, we generated tumors in vivo with a combination of human M2 macrophages mixed with either Raji or SKOV3 human tumor cells." (PMID 40408355, 2025). "For example, SIRPA interacts with CD47 to provide a “do not eat me” signal, helping dormant tumor cells evade macrophage-mediated phagocytosis." (PMID 39273449, 2024). "It is postulated that the secreted SIRPα-Fc and Siglec10-Fc blocked the corresponding “do not eat me” signals and thus restored TAM‐mediated tumor cell phagocytosis." (PMID 38016957, 2023). "The major purpose for the design of 6MW3211 is to obtain therapeutic benefit by selectively blocking the interaction of CD47 and SIRPα on PD-L1 and CD47 double positive tumor cells, but not binding to CD47 expressing on RBCs and other normal cells." (PMID 36593962, 2023). "On the other hand, The SIRPA/CD47 pathway is defined as the signal ‘do not eat me’, which recognizes CD47-expressing tumor cells as self-normal cells and results in the inhibition of phagocytosis." (PMID 37958467, 2023). "The co-culture of live LN-229 with parental HMC3, SIRPα-negative and MERTK-negative cells yielded low % GFP+ CD40+ cells (~5%), indicating low activities of tumor phagocytosis." (PMID 37483607, 2023). "Enhanced M1 phagocytosis can be achieved by stimulating calreticulin or phosphatidylserine in tumor cells, or by blocking the CD47/SIRPα (“Do not eat me”) signaling axis." (PMID 37457707, 2023). "Hyperactivated CD47/SIRPα and PD1/PD‐L1 signals in CD68+ TAMs in tumor tissues are negative prognostic markers for ICCs after resection." (PMID 35317832, 2022). "As a new SIRPα-Fc fusion protein targeting the CD47/SIRPα pathway, IMM01 exhibited strong dual-functional anti-tumor activity through phagocytosis by blocking the “do not eat me” signal and activating the “eat me” signal." (PMID 36080360, 2022). "Although M1 TAMs possess the ability to kill tumor cells, the clever tumor cells can express CD47, which binds to SIRPα on the macrophage surface to release the signal: “do not eat me”." (PMID 35859703, 2022). "The phagocytic function of macrophages is regulated by the inhibitory receptor signaling regulatory protein α (SIRPα) expressed on macrophages, whose ligand is CD47, a “do not eat me” signal, overexpressed on tumor cells." (PMID 35965509, 2022). "According to MPM patients, we also observed that both SIRPα and the “do not eat me” signal CD47 were, respectively, expressed by Mo-TAMs and tumor cells." (PMID 33922336, 2021). "On the contrary, TAX2 treatment did not impact macrophage tumor recruitment, which appears to be consistent with TAX2 molecular mode of action that does not affect CD47 binding to its macrophage counter-receptor SIRPα." (PMID 34638503, 2021). "TAM repolarization is apparently independent of which arm of the CD47-SIRPα interaction is targeted, as this phenotype was also described for mice treated with an antibody against SIRPα in a RENCA tumor model." (PMID 30133535, 2018). "The SIRPα end of the ARC bound immobilized CD47 at 3.59 nM affinity and also CD47 on the surface of human tumor cells both in vitro and in vivo, but importantly, did not bind human platelets, RBCs, nor induce hemolytic activity." (PMID 30400822, 2018).